INS (insulin)
Diseases named in the same sentence as INS in open-access papers (continued):
Sharing a sentence is not in itself a finding about the gene and the disease.
Hyperglycemia (continued). "Maternal hyperglycemia is able to induce fetal hyperglycemia due to an increased transplacental transfer of glucose, while maternal insulin is not able to cross the placenta." (PMID 22970290, 2012). "Conversely, some other studies disclose that lack of insulin or hyperglycemia in type 1 DM results in lower Akt activities." (PMID 19965962, 2011). "Administration of exogenous insulin is the fundamental means of treating hyperglycaemia in type 1 diabetes, but it does not restore the physiological regulation of blood glucose." (PMID 21716654, 2011). "Though fasting concentrations and subsequent HOMA calculations offer only gross approximations of insulin sensitivity, these findings indicate that neither hyperglycemia nor hyperinsulinemia are likely to be key factors influencing primary outcomes." (PMID 21649916, 2011). "Administration of insulin infusions to PN patients with hyperglycemia in the noncritically-ill setting would be a significant burden on the system, given the extra monitoring required and nursing care involved." (PMID 20811546, 2011). "Insulin was not required and hyperglycemia did not recur during the follow-up period of about two years." (PMID 21448333, 2011). "Forty-eight hours after admission, the percentage of children with hyperglycemia had decreased from 33% to 8% without insulin therapy." (PMID 21276273, 2011). "Nevertheless, a previous study has shown that most wild-type mouse strains, including B6 and BALB, do not develop significant hyperlipidemia or hyperglycemia on a high fat diet, although they exhibit increased insulin release." (PMID 22204493, 2011). "The Tally Ho mice investigated in the current study although hyperglycemic did not have elevated insulin levels thus suggesting that expression of SLMAP is affected by hyperglycemia and not insulin." (PMID 21785580, 2011). "Previous studies have concentrated on the insulin mimetic properties of visfatin, due to the original work by Fukuhara and co-workers, with subsequent human studies noting increased circulating visfatin concentration in states of hyperglycemia and T2DM, which reduced with insulin treatment." (PMID 21694775, 2011). "Future studies should investigate the mechanisms of hyperglycaemia related microglial apoptosis, particularly the impaired downregulation of GLUT, and assess the neuropathological as well as neurological effects of BG control by insulin therapy." (PMID 21612615, 2011). "In Group II animals, there was decrease in protein expression of PI3K and AKT when compared to Group III, indicating the insufficiency of insulin to maintain the normal signaling and the uptake of glucose through GLUT4 in the muscles of the animals which results in hyperglycemia." (PMID 20924498, 2011). "We have assessed blood glucose and insulin levels to understand whether ginger ameliorated cataract onset and progression by reducing STZ-induced hyperglycemia." (PMID 20806076, 2010). "Dr. Pratibha Singhi, Professor of Pediatrics: Hyperglycemia can occur with sepsis and severe stress; it is not uncommon in children, who even require insulin and drugs." (PMID 20835329, 2010). "In the presence of hyperglycemia, when dieting errors and improper oral therapeutics are excluded, it is suggested to administer the second dose of NPH insulin before breakfast, which must be a 4-unit dose, and to maintain oral agents, progressively increasing the dose according to self-monitoring." (PMID 20718958, 2010). "In the absence of pancreatic functional reserve, the pancreas fails to produce insulin levels with relative hypoinsulinism in the second half of pregnancy with consequent maternal hyperglycemia, characterizing DMG." (PMID 20416073, 2010). "In the absence of exogenous insulin, patients with type 1 diabetes exhibit a variety of metabolic abnormalities including hyperglycemia, glycosurea, accelerated ketogenesis, and muscle wasting due to increased proteolysis." (PMID 20479934, 2010).
Hyperglycemia (continued). "Data show that both RS and DS reduce body weight without affecting food intake and also lead to hyperglycemia and decreased insulin levels during an IVGTT." (PMID 20339560, 2010). "Early treatment with insulin in preterm infants (without hyperglycemia) even showed higher mortality at 28 days in the early-insulin group than in the control group." (PMID 20646308, 2010). "Since hyperglycemia was treated with administration of exogenous insulin in both groups to achieve normal levels, we did not expect significantly different glucose levels between patients, as observed." (PMID 20701787, 2010). "Thirty-three survivors treated with insulin for hyperglycemia and 63 matched controls without hyperglycemia were evaluated at a corrected age of 2 years." (PMID 20646308, 2010). "Acute sleep disturbance also caused hyperglycemia during an IVGTT, yet, without affecting the insulin response." (PMID 20339560, 2010). "In this case, there was no corresponding increase in serum insulin, and as a result, the animals displayed a frank prediabetic profile, characterized by hyperglycemia and impaired glucose and lipid utilization." (PMID 20123610, 2010). "One, we cannot control exogenous insulin dosing with the fine specificity required to achieve BG control close to that achieved by a healthy pancreas; postprandial hyperglycemia is particularly difficult if not impossible to control in a mouse." (PMID 19287497, 2009). "More interestingly, short term insulin replacement therapy in diabetic NOD mice reversed hyperglycemia, yet regularly failed to promptly normalize β-cell proliferation (pellet, early)." (PMID 19287497, 2009). "When episodes of hyperglycemia are not extended, granular exocytosis is balanced by formation of new insulin granules resulting in maintained insulin content." (PMID 19607692, 2009). "Even though these patients produce high levels of insulin, it is not enough to correct hyperglycaemia, and therefore they too display some evidence of relative beta-cell dysfunction." (PMID 19245691, 2009). "One recent publication documented the production of insulin expressing cells sufficient to improve, although not normalise, hyperglycaemia in diabetic mice through an adeno-rat Pdx-1 recombinant virus." (PMID 18628974, 2008). "Madera's physician was concerned about his hyperglycemia and recommended the initiation of basal insulin therapy rather than the addition of a second OAD." (PMID 18279520, 2008). "In 92% of the insulin-treated patients, hyperglycaemia was present on admission (86% in the noninsulin treatment group) and in all patients on at least one of the following 10 days in the intensive care unit." (PMID 18218076, 2008). "Unlike the rats treated with streptozotocin, those treated with alloxan on the 4th or 6th day of life showed increased longevity coupled with persistent hyperglycemia, since insulin production by pancreatic β cells did not normalize." (PMID 18828926, 2008). "The lack of insulin leads to chronic hyperglycemia and secondary complications, such as cardiovascular disease." (PMID 17941991, 2007). "It has been known for decades that following trauma, hyperglycemia without increased insulin secretion occurs, and that the degree of hyperglycemia is correlated with the severity of the injury." (PMID 16111485, 2005). "Insulin dosing aims to achieve the maximum tolerable dose to maintain a low HbA1c, control postprandial hyperglycemia without inducing hypoglycemia, minimize catabolism, and preserve optimal nutrition and pulmonary health without restricting carbohydrate intake." (PMID 41552835, 2026). "Moreover, the effects of chronic hyperglycaemia on insulin secretion and metabolic gene expression (but not insulin content) were largely reversed by subsequent inhibition of glucokinase." (PMID 41891907, 2026).
Hyperglycemia (continued). "Given that rosiglitazone affects multiple organs and acts as an insulin sensitizer, it is not clear whether correction of hyperglycemia is the only factor responsible for the upregulation of renal NEP protein expression observed in db/db mice." (PMID 41601953, 2026). "Furthermore, hyperglycemia in extremely low birth weight (ELBW) infants is common even in the absence of lipid infusion, due to factors such as stress, infections, steroid use, and insulin resistance." (PMID 40567525, 2025). "Notably, the WT + D2 mice maintained marked hyperglycemia throughout the study despite insulin administration, a pattern not observed in the SerpinA3k KO mice." (PMID 41329353, 2025). "Thus, our model is consistent with the observation that a similar remission is seen in insulin treatment of patients with similar demographics to KPD patients who present with severe hyperglycemia, but not ketoacidosis." (PMID 38895272, 2025). "New-onset hyperglycemia after SARS-CoV-2 infection may be attributed to the ability of the virus to successfully invade beta cells, abduct their intracellular mechanisms and disrupt their insulin production." (PMID 40469441, 2025). "The mechanism of the restoration of impaired insulin secretion in these cases was postulated to be the early normalization of hyperglycemia at the onset of the disease that enabled the restoration of impaired pancreatic β-cells or the regeneration of severely damaged pancreatic β-cells." (PMID 40406776, 2025). "We propose that the increased susceptibility of T2D patients to developing PD may not be primarily due to hyperglycemia, but rather due to insulin resistance or the interaction between IAPP and α-synuclein and/or tau." (PMID 39847072, 2025). "However, even though the mice were insulin-resistant, NO3− did prevent hyperglycemia entirely." (PMID 40806018, 2025). "Insulin inhibits transcription factor NF-kB and reduces the production of inflammatory cytokines, inhibits NRL inflammasome formation, decreases leukocyte adhesion to the endothelium, and prevents hyperglycaemia-induced production of reactive oxygen species and advanced glycation end products." (PMID 40565766, 2025). "This was also the case for most described patients with YIPF5-MEDS; however, a recent report described an individual with a homozygous YIPF5 missense variant who, in addition to microcephaly and epilepsy, had illness-induced hyperglycemia, with no insulin requirement between episodes." (PMID 40924476, 2025). "Post-surgery, islet function was categorized into three groups: insulin-independent for those not using insulin, partial islet function for those with hyperglycemia managed by daily insulin or C-peptide positive, and insulin-dependent for those requiring standard insulin therapy." (PMID 40747090, 2025). "Thus, PHNH should be ruled out in patients on insulin therapy who present with dawn hyperglycemia, as stated by Michael Somogyi in the twentieth century." (PMID 40465171, 2025). "In contrast to people, no dog received insulin despite a high proportion exhibiting hyperglycemia." (PMID 41368848, 2025). "However, hyperglycemia was still observed from midnight to 5 AM, likely due to carbohydrate intake without bolus insulin administration." (PMID 40822948, 2025). "The results taken altogether suggest that M. charantia may reduce hyperglycaemia by improving insulin sensitivity without directly affecting the pancreatic β-cell function." (PMID 41280283, 2025). "We not only focus on adequate tailoring of insulin therapy adapted at the time of PD exchange with hypertonic glucose solution., but also emphasize the use of continuous glucose monitoring (CGM) that allows assessment of mean glucose values and time spent in normal, hypo, and hyperglycemia." (PMID 40430224, 2025). "Notably, studies using glucagon receptor–deficient (GCGR-/-) mouse models have demonstrated that inhibiting glucagon action can ameliorate hyperglycemia even in the absence of insulin." (PMID 40822953, 2025).
Hyperglycemia (continued). "Insulin treatment may potentially control AMR through restoring immune function, which is highlighted by previous studies showing that treatment with insulin at doses that do not resolve hyperglycemia still resolves immune cell dysfunction." (PMID 39937900, 2025). "Insulin was successfully discontinued in six months without any recurrence of hyperglycemia." (PMID 40777711, 2025). "Despite the absence of hyperglycemia in EuDKA, insulin remains a critical component of treatment." (PMID 40725973, 2025). "However, there is a different view that in the state of hyperglycemia, the overactivation of ERK1/2 may lead to the dysfunction of islet β cells, including impaired insulin secretion and apoptosis." (PMID 40417223, 2025). "The differential glucagon response in single vs group housed mice without altered insulin, indicates that engagement of pancreatic α-cells could drive fasting hyperglycemia during chronic isolation." (PMID 41509225, 2025). "PDHA1 knockout mice (bKO) display glucose intolerance and markedly reduced pancreatic secretion but no decrease in insulin sensitivity, indicating that hyperglycemia in bKO mice results from β-cell dysfunction and insulin secretion imbalance rather than peripheral tissue insulin resistance." (PMID 41268170, 2025). "However, none of the patients in this study required insulin therapy or experienced prolonged hospital stays due to hyperglycemia." (PMID 40225449, 2025). "This novel subgroup appeared to be relatively insulin-sensitive in the fasting state but developed marked post-load hyperglycaemia and hyperinsulinaemia, suggesting an isolated postprandial defect in insulin sensitivity that was not captured by HOMA2-B or HOMA2-S." (PMID 39621104, 2025). "Insulin fails to suppress the expression of Pepck and G6pc1 mRNA during the refeeding period, leading to greater glucose release into circulation, resulting in hyperglycemia." (PMID 40507838, 2025). "Fifth, while our GDM model was based on a well-validated protocol and hyperglycemia was confirmed at the time of model induction, we did not perform longitudinal profiling of peripheral metabolic parameters such as plasma insulin, glucose tolerance, or asprosin levels." (PMID 41399726, 2025). "Prior studies on STZ-induced rat models show that the 65 mg/kg dose achieves substantial β-cell destruction (about 84% reduction in pancreatic insulin content within 24 h), leading to long-lasting hyperglycemia and a stable T1DM phenotype without excessive mortality." (PMID 41162165, 2025). "Combined CGM/SIP data revealed several issues: missed or delayed pre-prandial insulin aspart doses, administration of insulin aspart when hypoglycemic (without correction), and consumption of high-carbohydrate snacks not covered by prandial insulin leading to severe hyperglycemia." (PMID 40142601, 2025). "Mechanistic hypotheses – including hyperglycaemia and exogenous insulin – are not conclusively established." (PMID 41334715, 2025). "The results of this meta-analysis indicate that dietary carbohydrates (NFE), included between 2.8% and 57% ME, are not a risk factor for greater BFM, fasted insulin, and glucose concentrations in cats, suggesting that NFE does not pose a risk for feline obesity, IR, or hyperglycemia." (PMID 40052519, 2025). "Losartan may offer mild improvements in insulin sensitivity, but its action does not significantly lower blood glucose levels nor alleviate the compensatory mechanisms driven by hyperglycemia." (PMID 40650071, 2025). "Increased plasma levels of glucagon‐like peptide 1 (GLP‐1) and FGF‐21 were found to contribute to the improved glycemic control in Gcgr−/− mice and to work in a complementary way to prevent postprandial hyperglycemia in mice lacking insulin and glucagon action." (PMID 39985139, 2025). "While conventional insulin therapy manages hyperglycemia, it fails to halt autoimmunity." (PMID 41012130, 2025).
Hyperglycemia (continued). "Importantly, the reduced insulin delivery during Ease-off did not lead to significant hyperglycaemia, as the mean time above 180 mg/dL was 15% and the median time above 250 mg/dL was 1%." (PMID 39146468, 2025). "We did not include insulin as a category of anti-hyperglycemia medications." (PMID 39910396, 2025). "However, insulin dosing based on carbohydrate counting fails to compensate for delayed hyperglycemia from protein and fat." (PMID 41156539, 2025). "Here, we show that Gc ablation had systemic insulin-sensitizing effects to prevent weight gain, hyperglycemia, and glucose intolerance; lower nonesterified fatty acids and triglycerides; and augment glucose uptake in skeletal muscle and adipose in male mice fed a high-fat diet." (PMID 41355800, 2025). "SARS-CoV-2 infection may also promote hyperglycemia by inducing excess hepatic glucose production through gluconeogenesis or glycogenolysis independent of pancreatic function or insulin effects." (PMID 39164284, 2024). "However, when the blood glucose level dramatically fluctuates from hypoglycemia to hyperglycemia under insulin administration rather than remaining continuously hyperglycemic, steroid therapy should be considered to stop diarrhea." (PMID 39575018, 2024). "The older sibling presented with high-grade fever and right ankle pain, possibly indicative of a calcified deposit, alongside complications such as hyperglycemia (managed without insulin) and moderate pulmonary arterial hypertension (PAH) with tricuspid regurgitation (TR)." (PMID 39791064, 2024). "Additionally, this study did not account for factors such as chronic alcohol consumption, cigarette smoking, and secondhand smoke exposure, which are known to affect hyperglycemia and DPN via mechanisms like enhanced insulin resistance and inflammatory responses." (PMID 39559714, 2024). "Importantly, whereas 3d HFD triggered post-absorptive hyperglycemia and enhanced glucose-induced insulin release in control animals, Drp1MGKO failed to mount a comparable whole body metabolic response." (PMID 37066282, 2024). "In addition to 11 mg of phentolamine mesylate, a total of 5 units of insulin was intraoperatively used to prevent hyperglycemia, but the amount was not enough to affect postoperative blood glucose level." (PMID 39498182, 2024). "Although other reports suggest that hyperglycemia alone can stimulate stellate cells, incubating HSCs in media enriched with high glucose concentrations did not alter type I collagen promoter activity in the absence of insulin." (PMID 40808720, 2024). "However, the amount of serum insulin was increased in imeglimin-treated, but not metformin-treated, db/db mice, suggesting that imeglimin and metformin ameliorate hyperglycemia through different mechanisms in db/db mice." (PMID 38485716, 2024). "The patient also reported that he could not reduce insulin doses to the same extent as when montelukast was initiated earlier in 2022 but did report that hyperglycemia after meals became less pronounced." (PMID 39749265, 2024). "Healthcare workers should be mindful of increased insulin requirements following prone positioning in critically ill patients, where hyperglycaemia may be detrimental if not monitored attentively." (PMID 39532941, 2024). "Mice lacking Lrp5 in osteoblasts had hyperglycaemia, reduced glucose tolerance and insulin sensitivity reinforcing a link between the Wnt signalling pathway and osteoblast insulin signalling suggesting it could influence whole-body glucose homeostasis." (PMID 39588310, 2024). "Another prospective randomized clinical trial in adults demonstrated that subcutaneous administration of insulin glargine within the first 12 hours of intravenous insulin infusion significantly decreased rebound hyperglycemia after discontinuation of intravenous insulin, with no adverse effects." (PMID 40433420, 2024).